CD209 (CD209 molecule)
Diseases named in the same sentence as CD209 in open-access papers (continued):
Sharing a sentence is not in itself a finding about the gene and the disease.
infectious disease (14 papers, 2008 to 2025). A disorder directly resulting from the presence and activity of a microbial, viral, or parasitic agent in humans. "Further studies are imperative, before a definitive argument can be made, whereby other infectious diseases are examined viz-a-viz genotypic and allelic diversities of CD209 gene promoter polymorphism in the African population." (PMID 25755928, 2015). "All but the M. leprae case-control study found an association of the CD209 -336A/G promoter SNP with infectious disease susceptibility or protection." (PMID 18167547, 2008). "The higher frequency of CD209 homozygote mutant variants in the African control group reveals a potential impairment of the capacity to mount an immune response to infectious diseases, and possibly delineate susceptibility to or severity of infectious co-morbidities within and between groups." (PMID 25755928, 2015). "CD209 is a C-type lectin receptor of dendritic cells involved in early stages of numerous infectious diseases." (PMID 36110142, 2022). "Variations in the CD209 promoter (−336 A/G; rs4804803) genotype are involved in the pathogenesis of human infectious diseases." (PMID 21245921, 2011). "Regarding infectious diseases, position −336 in the promoter region of the CD209 gene has been studied extensively." (PMID 19264667, 2009). "The C-type lectin DC-SIGN (CD209) is known to be the major dengue receptor on human dendritic cells, and a single nucleotide polymorphism (SNP) in the promoter region of CD209 (−336 A/G; rs4804803) is susceptible to many infectious diseases." (PMID 21245921, 2011). "The higher frequency of CD209 gene promoter homozygote mutants in the non-SCD group reveals an impaired capacity to mount an immune response to infectious diseases, potentially a contributor to the dominance of infectious co-morbidities in this population." (PMID 25755928, 2015).
bacterial infection (8 papers, 2014 to 2025). "The functions of On-LECT2 in the immune response of Nile tilapia against bacterial infection was further determined by detecting the expression patterns of the potential receptors CD209 and CLR via qRT-PCR." (PMID 34093564, 2021). "The relative MoDC vs. Mo/MP signature encompasses additional genes that participate in “migration of cells” (p = 10−2.3, with S1PR3, CCL17, and SLC2A1), “bacterial infection” (p = 10−3.2, with CD1B, CD209, and FCGR2B), and “synthesis of nitric oxide” (10−2.5, with PLAU, IL1R2, and NOS2)." (PMID 26150816, 2015).
hematologic malignancy (2 papers, 2012 to 2020). "Three studies have demonstrated that CLEC7A (Dectin-1) or CD209 (DC-SIGN) variants are associated with the development of IA in patients with hematologic malignancies, and this is further supported by a study finding decreased CLEC7A expression in hematologic malignancy patients with IA." (PMID 32185141, 2020).
CD209 also shares sentences with these, for which no sentence is quoted: measles (7 papers); fungal infections (6); AIDS (5); pulmonary aspergillosis (5); Autoimmunity (4); Allergy (3); cutaneous melanoma (3); diabetes (3); Ebola (3); Flavivirus Infections (3); hepatocellular carcinoma (3); inflammatory bowel disease (3); lupus (3); prostate carcinoma (3); psoriatic arthritis (3); pulmonary tuberculosis (3); adenocarcinoma (2); B-cell lymphoma (2); bladder cancer (2); co-infection (2); colitis (2); coronary artery disease (2); cutaneous T-cell lymphoma (2); dermatofibrosarcoma protuberans (2); endometriosis (2); follicular lymphoma (2); glioblastoma (2); HELLP syndrome (2); lung adenocarcinoma (2); lymphoma (2).
A further 95 diseases each share a sentence with CD209 in 2 papers or fewer.